EFCAB7 (EF-hand calcium binding domain 7)
Description:
Component of the EvC complex that positively regulates ciliary Hedgehog (Hh) signaling. Required for the localization of the EVC2:EVC subcomplex at the base of primary cilia.
Synonyms: KIAA1799; RP4-534K7.1
Tractability: Antibody: UniProt places it where antibodies can reach, with medium confidence; its Gene Ontology location is reachable by antibodies, with medium confidence. PROTAC: ubiquitination databases record sites on it.
Gene: Protein-coding gene on chromosome 1 (63,523,372 to 63,572,693, forward strand). Ensembl gene ENSG00000203965.
Subcellular location: Cell projection, cilium membrane
Subcellular location (Human Protein Atlas): Cytosol; Primary cilium
Pathways (Reactome):
Signal Transduction: Activation of SMO
Gene Ontology:
Molecular function: calcium ion binding
Biological process: positive regulation of protein import into nucleus; positive regulation of protein localization to ciliary membrane; positive regulation of transcription by RNA polymerase II; protein localization to motile cilium; regulation of smoothened signaling pathway
Cellular component: ciliary membrane; cilium; cytoplasmic side of plasma membrane; plasma membrane protein complex
Genetic constraint (gnomAD): Loss-of-function variants: 44 observed, 50.89 expected, observed/expected ratio (o/e) 0.86, 90% interval 0.68 to 1.11. The upper end of that interval is the gene's LOEUF score, 1.11, which puts it in group 4 of 6, group 1 being the genes least tolerant of losing a copy. Missense variants: 514 observed, 580.98 expected, observed/expected ratio (o/e) 0.88, 90% interval 0.82 to 0.95. Synonymous variants: 170 observed, 194.62 expected, observed/expected ratio (o/e) 0.87, 90% interval 0.77 to 0.99.
Homologues: Orthologues: chimpanzee EFCAB7 (99% identical), dog EFCAB7 (90% identical), pig EFCAB7 (88% identical), mouse Efcab7 (83% identical), rabbit EFCAB7 (82% identical), rat Efcab7 (80% identical), guinea pig EFCAB7 (77% identical), tropical clawed frog pgm1 (62% identical), zebrafish efcab7 (53% identical), Caenorhabditis elegans E02A10.3 (7% identical), Caenorhabditis elegans B0563.7 (6% identical), Caenorhabditis elegans F35C12.3 (6% identical), and 5 more. Paralogues in human: EFCAB12 (12% identical), CETN1 (7% identical), EFCAB3 (7% identical), CETN2 (7% identical), CALM1 (7% identical), CALM2 (7% identical), CALM3 (7% identical), CABP1 (7% identical), CABP2 (7% identical), CABP5 (6% identical), CETN3 (6% identical), CABP4 (6% identical), and 8 more.
Diseases named in the same sentence as EFCAB7 in open-access papers:
EFCAB7 is named in the same sentence as 3 diseases in open-access papers, as found by Europe PMC text mining. Sharing a sentence is not in itself a finding about the gene and the disease. The quoted sentences say what the papers report.
liver cancer (1 paper, 2024). An epithelial or non-epithelial malignant neoplasm that arises from the liver. "Subsequently, we conducted CO-IP experiments, which confirmed that EFCAB7 directly binds to PARK7 in liver cancer cells, consistent with the mass spectrometry results." (PMID 39276379, 2024). "mRNA expression of EFCAB7 was compared in different liver cancer cell lines." (PMID 39276379, 2024).
tumor (2 papers, 2018 to 2024). "Intriguingly, PARK7 overexpression substantially increased cell growth in EFCAB7 knockdown tumor cells." (PMID 39276379, 2024). "Remarkably, EFCAB7 was significantly upregulated in tumor tissues after radiofrequency ablation (P<0.001)." (PMID 39276379, 2024). "Similar to the findings in vitro, groups silencing EFCAB7 markedly inhibited tumor cell growth in vivo." (PMID 39276379, 2024). "Then, many proteins were found to interact with EFACB7 in HCC tumor cell lines via mass spectrometry and bioinformatics analyses indicating that EFCAB7 participated in many vital biological processes during tumor development." (PMID 39276379, 2024). "Consistent with the Transwell Assay results, data from the wound healing assay also confirmed the crucial role of EFCAB7 in tumor cell metastasis." (PMID 39276379, 2024). "To confirm this hypothesis, we compared the cell migration capacity of tumor cells between the EFCAB7 knockdown groups and the control groups using Transwell Assay." (PMID 39276379, 2024). "To date, EFCAB7 was found to serve as an oncogene and might influence tumor cell proliferation, apoptosis, and metastasis." (PMID 39276379, 2024). "Given that EFCAB7 is significantly upregulated after RFA and our previous results have shown that EFCAB7 promotes liver cell growth, we further investigated whether EFCAB7 could also enhance tumor cell metastasis." (PMID 39276379, 2024). "Finally, when we overexpressed PARK7 in EFCAB7 knockdown tumor cells, it rescued proliferation and metastasis, indicating a functional relationship between these two genes." (PMID 39276379, 2024). "Then, EFCAB7 promoted HCC tumor cell proliferation and metastasis while inhibiting apoptosis." (PMID 39276379, 2024). "EFCAB7 was observed to influence tumor cell growth in vitro." (PMID 39276379, 2024). "In the TCGA database, EFCAB7 was highly expressed in HCC tissues than in para-tumor tissues." (PMID 39276379, 2024). "Furthermore, we found that PARK7 overexpression enhanced cell migration in EFCAB7 knockdown tumor cells." (PMID 39276379, 2024). "However, the role of EFCAB7 in tumor development and malignancy transformation is still unclear." (PMID 39276379, 2024). "In this study, it was found that EFCAB7 is greatly upregulated in HCC tissues after radiofrequency ablation, proving the potential protective role of this protein during intrinsic tumor cell-mediated escape after thermal ablation." (PMID 39276379, 2024). "Based on these findings, 11 pairs of tumor and adjacent tissues before RFA and after RFA were collected for assessing mRNA expression of APC, FAS, HGF, PCNA and EFCAB7." (PMID 39276379, 2024). "The results clearly indicated that tumor cells lacking EFCAB7 had a significantly reduced ability to invade." (PMID 39276379, 2024).
EFCAB7 also shares sentences with these, for which no sentence is quoted: hepatocellular carcinoma (1 paper).